MIR25 (microRNA 25)
Synonyms: hsa-mir-25; MIRN25; miR-25
Gene: MicroRNA gene on chromosome 7 (100,093,560 to 100,093,643, reverse strand). Ensembl gene ENSG00000207547.
Gene Ontology:
Biological process: miRNA-mediated post-transcriptional gene silencing
Cellular component: RISC complex
Homologues: Orthologues: chimpanzee ptr-mir-25 (100% identical), guinea pig MIR25 (100% identical), mouse Mir25 (100% identical), macaque mml-mir-25 (99% identical), pig MIR25 (99% identical), rabbit MIR25 (99% identical), zebrafish mir25 (76% identical), tropical clawed frog xtr-mir-25-1 (73% identical), dog MIR25 (69% identical). Paralogues in human: MIR92A2 (38% identical), MIR92A1 (37% identical).
Diseases named in the same sentence as MIR25 in open-access papers:
MIR25 is named in the same sentence as 3 diseases in open-access papers, as found by Europe PMC text mining. Sharing a sentence is not in itself a finding about the gene and the disease. The quoted sentences say what the papers report.
gastric cancer (1 paper, 2019). A primary or metastatic malignant neoplasm involving the stomach. "Previous study has shown that SLC34A2 could target the MIR25 promoter to promote gastric cancer progression 19; we wondered whether the SLC34A2–miR‐25 axis exists in neuroblastoma cells." (PMID 30868061, 2019). "Mechanistically, we found that SLC34A2 could directly bind to the promoter of MIR25 and thus upregulate its level, which is consistent with the previous study showing that SLC34A could regulate miR‐25 activity to affect gastric cancer progression." (PMID 30868061, 2019).
neuroblastoma (1 paper, 2019). Neuroblastoma (NB) is the most common solid, extracranial childhood tumor. "In conclusion, our results indicate that SLC34A2 could directly bind to the promoter of MIR25 and thus facilitate miR‐25–Gsk3β axis‐mediated activation of Wnt signaling, which is responsible for the SLC34A2‐mediated effects on the stemness of neuroblastoma cells." (PMID 30868061, 2019).
prostate carcinoma (1 paper, 2021). A carcinoma that arises from epithelial cells of the prostate gland. "Recently, many ncRNAs, such as MALAT1, NEAT1, MIR25, and LET-7, are found to be associated with prostate cancer." (PMID 34576294, 2021).